ADAM11 (ADAM metallopeptidase domain 11)
Description:
Probable ligand for integrin in the brain. This is a non catalytic metalloprotease-like protein. Required for localization of the potassium channel subunit proteins KCNA1/KV1.1 and KCNA2/KV1.2 at cerebellar cortex basket cell distal terminals, is thereby involved in ephaptic inhibitory synchronization of Purkinje cell firing and response to stress (By similarity). Plays a role in spatial learning and motor coordination (By similarity). Involved in the nociceptive pain response to chemical-derived stimulation (By similarity).
Synonyms: MDC
Tractability: Antibody: its Gene Ontology location is reachable by antibodies, with high confidence; UniProt places it where antibodies can reach, with medium confidence; UniProt predicts a signal peptide or a membrane-spanning region. PROTAC: its protein half-life has been measured.
Gene: Protein-coding gene on chromosome 17 (44,758,988 to 44,781,846, forward strand). Ensembl gene ENSG00000073670.
Subcellular location: Presynaptic cell membrane; Perikaryon; Cell projection, axon
Pathways (Reactome):
Developmental Biology: LGI-ADAM interactions
Gene Ontology:
Molecular function: integrin binding; metalloendopeptidase activity; metallopeptidase activity
Biological process: behavioral response to acetic acid induced pain; behavioral response to formalin induced pain; establishment of protein localization; integrin-mediated signaling pathway; multicellular organismal response to stress; proteolysis
Cellular component: extracellular matrix; perikaryon; plasma membrane; presynaptic membrane; axon
Genetic constraint (gnomAD): Loss-of-function variants: 49 observed, 106.44 expected, observed/expected ratio (o/e) 0.46, 90% interval 0.37 to 0.58. The upper end of that interval is the gene's LOEUF score, 0.58, which puts it in group 2 of 6, group 1 being the genes least tolerant of losing a copy. Missense variants: 772 observed, 976.61 expected, observed/expected ratio (o/e) 0.79, 90% interval 0.74 to 0.84. Synonymous variants: 357 observed, 378.14 expected, observed/expected ratio (o/e) 0.94, 90% interval 0.87 to 1.03.
Homologues: Orthologues: chimpanzee ADAM11 (99% identical), pig ADAM11 (96% identical), mouse Adam11 (95% identical), macaque ADAM11 (94% identical), dog ADAM11 (94% identical), guinea pig ADAM11 (90% identical), rabbit ADAM11 (90% identical), rat Adam11 (88% identical), tropical clawed frog adam11 (65% identical), zebrafish adam11 (62% identical). Paralogues in human: ADAM22 (53% identical), ADAM23 (50% identical), ADAM19 (31% identical), ADAM33 (29% identical), ADAM12 (28% identical), ADAM9 (28% identical), ADAM15 (28% identical), ADAM8 (27% identical), ADAM21 (26% identical), ADAM28 (25% identical), ADAM30 (25% identical), ADAM20 (24% identical), and 8 more.
Diseases named in the same sentence as ADAM11 in open-access papers:
ADAM11 is named in the same sentence as 15 diseases in open-access papers, as found by Europe PMC text mining. Sharing a sentence is not in itself a finding about the gene and the disease. The quoted sentences say what the papers report.
Ataxia (2 papers, 2006 to 2023). Ataxia refers to impaired coordination of voluntary muscle movement. "ADAM11-deficient mice remained alive for more than one year without ataxia or tremor, but showed a deficit in spatial learning and motor dysfunction." (PMID 16504143, 2006). "ADAM11-deficient mice survived more than one year without ataxia or tremor, showed no abnormalities in body weight gain, spontaneous motor activity, muscle strength, or walking patterns, and exhibited no apparent anatomical-histological changes." (PMID 16504143, 2006). "Similar to EA1, the Adam11 mutant mouse, where KV1.1/1.2 is lost from the pinceau, responds to external stress with periods of ataxia." (PMID 37408217, 2023).
breast carcinoma (2 papers, 2023). "The ADAM11 gene was found to be associated with the molecular pathology of Breast cancer, epilepsy, and familial frontotemporal lobe." (PMID 37834358, 2023). "Given the previous observation that ADAM11 was mutated in two breast cancer samples, we further focused our analysis on data obtained from invasive breast carcinoma." (PMID 37766964, 2023).
melanoma (2 papers, 2022 to 2023). A malignant, usually aggressive tumor composed of atypical, neoplastic melanocytes. "Decreasing Adam11 in B16 mouse melanoma cells similarly increases cell proliferation by promoting the G1-S transition, a step controlled by CyclinD1." (PMID 37766964, 2023). "Using both human tumor data and mouse B16 melanoma cells, we further show that ADAM11 levels similarly correlate with Wnt or BMP4 activation levels." (PMID 37766964, 2023). "We used mouse B16 melanoma to test the function of Adam11 in cancer cells, and published database analysis to study the expression of ADAM11 in human tumors." (PMID 37766964, 2023). "To further test if Adam11 expression in cancer cells could modulate the Wnt signaling pathway, we used mouse B16 melanoma cells." (PMID 37766964, 2023). "With respect to the relationship between the level of baseline sPD-L1 and transcripts encoding 60 metalloproteases, ADAM11, ADAM20 and ADAMTS14 were identified as associated with higher baseline sPD-L1 levels in both CheckMate 009/RCC and CheckMate 038-P1/melanoma (t-values >1.5)." (PMID 35131863, 2022).
Obesity (2 papers, 2018). Accumulation of substantial excess body fat. "Although the Adam11 gene is known to be expressed in the mouse liver (MGI Gene Expression Database), its role in obesity and diabetes has not been discussed." (PMID 30526554, 2018).
childhood cancer (1 paper, 2023). "While this seems like an interesting strategy, we have also found that ADAM11 expression is increased in Neuroblastoma, a childhood cancer thought to be derived from neural crest cells." (PMID 37766964, 2023).
COVID-19 (1 paper, 2022). A disease caused by infection with severe acute respiratory syndrome coronavirus 2. "We found that the expression of the antiviral genes negatively correlated (except ADAM7, ADAM11, ADAM12, ADAM18, ADAM20, and ADAM29) with the HRCT score of the COVID-19 patients suggesting association of increased antiviral response with decreased disease severity." (PMID 36532041, 2022).
neuroblastoma (1 paper, 2023). Neuroblastoma (NB) is the most common solid, extracranial childhood tumor. "Similarly, in the neural crest derived tumor, neuroblastoma, ADAM11 expression is higher than in the normal tissue, with a concurrent increase in Smad1-5 expression and decreases in Sox3 expression." (PMID 37766964, 2023). "One type of tumor in which ADAM11 is increased rather than decreased is neuroblastoma (190 normal and 149 tumor samples, mean FC = 61.52 p = 6.94 10−56)." (PMID 37766964, 2023).
skin cutaneous melanoma (1 paper, 2023). "Furthermore, in skin cutaneous melanoma, published RNA-seq data shows a decreased level of ADAM11 and an increased level of CYCLIND1 between tumors (103 patients) and normal samples (474 patients)." (PMID 37766964, 2023).
tumor (7 papers, 2018 to 2024). "Originally, ADAM11 was recognized as a tumor suppressor gene candidate implicated in human breast carcinoma." (PMID 38317965, 2024). "Thirty years ago, ADAM11 was found to be mutated in two mammary gland tumors and was postulated to be a tumor suppressor." (PMID 37766964, 2023). "The genetic consequence of several of these 3′UTR variants affects the promoter region of the gene and encodes the candidate tumor suppressor gene, ADAM11." (PMID 37834358, 2023). "We also suggest inspecting the mechanisms underlying tumor-suppressing effects of some of the ADAMS such as ADAM-11 and ADAM-33, because despite their genetic basis of actions, their induced molecular pathways that appoint the suppressing effect has not been clear." (PMID 38317965, 2024). "Of these tumor size-associated cytokines, seven (TNF-β, MCP-3/CCL7, Fractalkine/CX3CL1, GRO/CXCL1, sCD40L, TGF-α, and MDC/ADAM11) were among those newly investigated as part of a bead array-based vitreous cytokine analysis of UM." (PMID 37509362, 2023). "Given our results showing that Adam11 regulates β-catenin activity in Xenopus embryos, we analyzed the expression of ADAM11 in available tumor expression data." (PMID 37766964, 2023). "In addition, we identified 15 cancer-related REGs in extremely large carnivores, including two tumor suppressor genes—ADAM11 and TEP1, of which ADAM11 was still significant after FDR correction." (PMID 34107880, 2021). "Lastly, the methylation analysis revealed that ADAM11, ADAM32, and ADAM33 exhibited higher levels of methylation in tumor tissues compared to normal tissues." (PMID 39346916, 2024). "Together, these results strongly suggest that Adam11’s ability to restrict β-catenin activity and delay EMT in the CNC is conserved in adult tissues and that loss of ADAM11 may contribute to β-catenin hyperactivation and CYCLIND1 overexpression, leading to tumor progression and metastasis." (PMID 37766964, 2023). "Potential tumor suppressor genes GAS7, RGS6, ADAM11 and FBXL2 are up-regulated in the lesser aggressive group L." (PMID 29844869, 2018). "Additionally, fifteen genes were associated with cancer control; among these, three were related to immunity (MAGT1, RFXANK and SKAP2), two (ADGRL3 and TENM3) were related to cell adhesion, and two (ADAM11 and TEP1) were found to be tumor suppressor genes." (PMID 34107880, 2021).
cancer (5 papers, 2021 to 2023). A tumor composed of atypical neoplastic, often pleomorphic cells that invade other tissues. "On the other hand, it would be interesting to test if increasing ADAM11 protein levels in cancer cells is sufficient to reduce β-catenin activity, CYCLIND1 expression, and cell proliferation." (PMID 37766964, 2023). "The human cancer analysis indicates a strong correlation between ADAM11 expression and CYCLIND1 levels." (PMID 37766964, 2023). "We propose that Adam11 maintains stem cell-like attributes in both CNC and cancer and that either an increase in Adam11 or a decrease in Adam11 can create an imbalance toward stemness or EMT, contributing to the cancer pathogenicity." (PMID 37766964, 2023). "We found low expression of the disintegrin and metalloproteinase families of the genes ADAM11 and ADAM32, which have relevance in cancer." (PMID 37047231, 2023). "Given the role of β-catenin in cancer and the known relation between EMT and cancer metastasis, we looked at human ADAM11 gene expression in available databases." (PMID 37766964, 2023). "Both ADAM11 and TEP1 had relatively higher evolutionary rates in extremely large carnivores than small ones and suggested an enhanced ability to suppress cancer." (PMID 34107880, 2021).
neurological disorder (1 paper, 2023). "This could partly explain the neurological disorder observed in mice lacking Adam11." (PMID 37766964, 2023).
ADAM11 also shares sentences with these, for which no sentence is quoted: diabetes (1 paper); epilepsy (1); invasive breast carcinoma (1); Tremor (1).